AKT1 (AKT serine/threonine kinase 1)
Diseases named in the same sentence as AKT1 in open-access papers (continued):
Sharing a sentence is not in itself a finding about the gene and the disease.
juvenile polyposis (1 paper, 2022). "Syndromes and corresponding genes include: SMAD4 (DPC4) and BMPR1A for juvenile polyposis (JPS), STK11 for Peutz–Jeghers (PJS) and PTEN and AKT1 for PTEN hamartomatous syndromes (PHS)." (PMID 36011318, 2022).
laminopathies (1 paper, 2012). "It has been suggested that aberrant phosphorylation of Ser458 of Lamin A by Akt1 contributes to striated muscle laminopathies caused by LMNA mutation." (PMID 23090008, 2012). "Therefore, inhibition of Akt1 by LY294002 might be beneficial to this and similar laminopathies." (PMID 23090008, 2012).
leprosy (1 paper, 2018). Leprosy is a chronic infectious disease affecting primarily the skin and peripheral nervous system. "In contrast, PIK3CA miRNAs were downregulated in all forms of leprosy in comparison to HS, and AKT1 miRNAs was more prominent in LL patient lesions." (PMID 29593724, 2018).
leukopenia (1 paper, 2024). "Notably, AKT1, EGFR, IL6, STAT3, BCL2, CASP3, and JUN were identified as the top seven targets (degree >80) and may be key targets of QJSB in treating leukopenia." (PMID 39295929, 2024).
megalencephaly-capillary malformation (1 paper, 2023).
Meningothelial Meningioma (1 paper, 2021). A WHO grade I meningioma characterized by the presence of tumor cells that form lobules. "The proportion of meningothelial meningiomas harboring AKT1, KLF4, SMO, or POLR2A mutations was significantly high." (PMID 33772057, 2021).
Middle East respiratory syndrome (1 paper, 2022). A viral respiratory infection that is caused by the MERS coronavirus (MERS-CoV), which most often manifests with moderate to severe respiratory symptoms, including productive cough and shortness of breath, which can progress to pneumonia and acute respiratory distress syndrome. "Moreover, deficiency of AKT1 significantly inhibits viral RNA expression, and PI3K/AKT kinase inhibitors are found to suppress the replication of middle east respiratory syndrome (MERS)." (PMID 35754492, 2022).
mucinous adenocarcinoma (1 paper, 2024). An invasive adenocarcinoma composed of malignant glandular cells which contain intracytoplasmic mucin. "Mucinous adenocarcinoma is characterized by AKT1 E17 K mutations." (PMID 38929710, 2024).
mucosal melanoma (1 paper, 2018). A melanoma that arises from a mucosal site. "In conclusion, p-Akt1 overexpression is an independent prognostic marker in mucosal melanomas and is significantly up-regulated in sinonasal melanomas." (PMID 30647870, 2018). "In conclusion, the results of the current study demonstrated that p-Akt1 overexpression is an independent prognostic marker in mucosal melanomas and is significantly up-regulated in sinonasal melanomas." (PMID 30647870, 2018).
ocular tumor (1 paper, 2009). "To determine whether phospho-AKT1 levels were increased in the tumors, we performed immunofluorescence studies on a 3-week-old fish with a trunk tumor showing strong GFP expression and on a 12-week-old fish with an ocular tumor showing weak GFP expression." (PMID 19555497, 2009).
ovarian disease (1 paper, 2023). "Additionally, the gene-diseasenetwork analysis showed that akt1 and tnf are master regulators of various disease pathways, such as HOTAIRregulatory pathways, AMPK signaling, growth failure, and autophagy,which are all indicative of severe ovarian disease due to ancestralBPA exposure." (PMID 37581432, 2023).
pancreatic NETs (1 paper, 2023).
papillary carcinomas of the breast (1 paper, 2023). "AKT1 and PIK3CA gene alterations, which are typically found in papillary carcinomas of the breast, were also not found." (PMID 37754277, 2023).
Peptic ulcer (1 paper, 2024). The term peptic ulcer refers to acid peptic injury of the digestive tract, resulting in mucosal break reaching the submucosa. "The PPI network was constructed for the peptic ulcer genes, the constructed network to show the interactions between peptic ulcer targets proved that the following genes have the higher node degrees; AKT1, TNF, SRC, EGFR, ESR1, PTGS2, MMP9." (PMID 38728332, 2024).
Photophobia (1 paper, 2024). Excessive sensitivity to light with the sensation of discomfort or pain in the eyes due to exposure to bright light. "When mRNA levels of Crebbp, Trpm3, Zmynd8 and Akt1 were compared between the two sexes, female photophobia mice showed significant lower levels than that of males." (PMID 39390364, 2024).
potassium deficiency (1 paper, 2014). A condition due to decreased dietary intake of potassium, as in starvation or failure to administer in intravenous solutions, or to gastrointestinal loss in diarrhea, chronic laxative abuse, vomiting, gastric suction, or bowel diversion. "Based on this indication, we tested well-established transcriptional read-outs of potassium deficiency in roots, the potassium influx transport proteins AKT1 and HAK5, and found that both were upregulated in sgn3." (PMID 25233277, 2014).
Q fever (1 paper, 2025). A bacterial infection caused by Coxiella burnetii. "It identified five hub genes (IL4, IL6, IL1B, CD28, and AKT1) that may contribute to the progression of Q fever by regulating immune responses." (PMID 41468478, 2025).
rectal NETs (1 paper, 2024).
reovirus infection (1 paper, 2021). "We next knocked down AKT1, AKT2, and AKT3 and examined the expression of IFN-β in BMDC followed by VSV or reovirus infection." (PMID 33976210, 2021). "Interestingly, expression of both AKT1 and AKT2 at mRNA level was reduced after VSV or reovirus infection." (PMID 33976210, 2021). "Knockdown of AKT3, but not AKT1 or AKT2, substantially reduced the enhanced expression of IFN-β at mRNA level in BMDC infected by VSV or reovirus, suggesting that AKT3 is the possible downstream target of PI3K activation after VSV or reovirus infection." (PMID 33976210, 2021).
respiratory allergy (1 paper, 2021). "According to the individual score, neither AKT1, MAPK13, nor STAT1 presented a high probability of promoting respiratory allergy on their own." (PMID 33936056, 2021).
Retinal hemorrhage (1 paper, 2019). Bleeding located within the retina. "Finally, mice lacking Akt1 showed severe retinal hemorrhage compared to the wild‐type." (PMID 30984553, 2019).
salmonellosis (1 paper, 2021). Infections with bacteria of the genus salmonella. "Resistance loci to systemic salmonellosis were mapped and refined to an 8kb, 14 gene region on chromosome 5, termed SAL1, including the CD27-binding protein and AKT1, a REAC-alpha serine/threonine protein kinase homolog, both involved in innate immune response signaling." (PMID 34867850, 2021).
sarcomatoid carcinoma (1 paper, 2015). A malignant epithelial neoplasm characterized by the presence of spindle cells and anaplastic morphologic features. "Eight sarcomatoid carcinoma were analyzed for the presence of EGFR kinase domain mutations, KRAS mutations, HER2 kinase domain mutations, BRAF mutations, ALK fusions, RET fusions and AKT1 mutations." (PMID 26486077, 2015).
Sinus bradycardia (1 paper, 2022). Bradycardia related to a mean resting sinus rate of less than 50 beats per minute. "There are 54 targets of action in the treatment of sinus bradycardia, of which 19 targets such as AKT1, IL6, TNF, and VEGFA are the core targets of Datura metel in the treatment of sinus bradycardia." (PMID 36626429, 2022). "The results of the network screening of core targets showed that AKT1, IL6, VEGFA, and TNF were the top 4 core target proteins in terms of degree value, and maybe the most core targets for the treatment of sinus bradycardia with Yohimbe." (PMID 36626429, 2022).
Skin rash (1 paper, 2016). A red eruption of the skin. "A four-genes model (rs884225 in EGFR 3′UTR, rs7787082 in ABCB1 intron, rs38845 in MET intron and rs3803300 in AKT1 5′UTR) was associated with TKIs induced ADRs and skin rash." (PMID 26988277, 2016).
skull base tumors (1 paper, 2025). "Genotype (p = 0.004) and WHO grade (p = 0.002) were significantly associated with tumor location: NF2 alterations predominated in convexity and spine, while TRAKLS mutations (TRAF7, AKT1, KLF4, SMO) were enriched in lower-grade skull base tumors." (PMID 40951339, 2025).
squamous cell carcinomas of the skin (1 paper, 2024). "Moreover, XPC knockdown in keratinocytes was associated with elevated levels of reactive oxygen species through altered AKT1 and NOX1 pathways, resulting in squamous cell carcinomas of the skin." (PMID 38672576, 2024).
Ta (1 paper, 2024). "In Ta tumors, the most frequent gene variants were FGFR3 (48%) and PIK3CA (26%), and the most common amplifications were AKT1 (24%), FGFR3 (13%), MYCN (11%), and CCND1 (11%)." (PMID 39410541, 2024).
tendinopathy (1 paper, 2025). "By intersecting the targets of NGR1 with those associated with tendinopathy, we constructed a PPI network, and the results showed that targets such as IL-6, TNF, AKT1, MMP9, and MMP3 are valuable in assessment." (PMID 40697661, 2025).
Tinnitus (1 paper, 2022). Tinnitus is an auditory perception that can be described as the experience of sound, in the ear or in the head, in the absence of external acoustic stimulation.
typhoid (1 paper, 2018). "In the first outbreak the markers with the most significant association with the fowl typhoid spanned the AKT1 gene." (PMID 30510562, 2018).
valvular heart disease (1 paper, 2022). "The present study demonstrated that the TSS and wall pressure in the LA change during valvular heart disease, resulting in upregulated mRNA and protein expression of IKCa2.3, IKCa3.1, AKT1, and P300." (PMID 35563689, 2022).
vasculitis (1 paper, 2022). "It is regarded that AKT1 exerts an essential role in the treatment of vasculitis with HXTLF." (PMID 36034958, 2022). "Based on PPI analysis, the overlapped genes with higher degrees in the hub gene network included MAPK1, MAPK3, VEGFA, TNF, and AKT1, implying that they were involved in the process of HXTLF treatment against vasculitis." (PMID 36034958, 2022). "The results demonstrated that HXTLF could inhibit the phosphorylation of AKT1, IKK, and NF-κB proteins, inhibit NETs formation, and reduce IL-1β concentration, indicating that AKT1 exerts a vital role in the treatment of vasculitis after HXTLF administration." (PMID 36034958, 2022). "Additionally, we activated and inhibited the AKT1 signaling pathway using the corresponding activator and inhibitor to explore the regulatory mechanism of HXTLF on AKT1 and other molecules in the treatment of vasculitis." (PMID 36034958, 2022). "Furthermore, we supplemented AKT1 activator (SC79) and inhibitor (MK-2206 2HCl) to interfere with the neutrophil growth, respectively, and discussed the relevant regulatory mechanism of HXTLF on vasculitis treatment." (PMID 36034958, 2022).
viral pneumonia (1 paper, 2026). Inflammation of the lung parenchyma that is caused by a viral infection. "Through the construction of a comprehensive PPI network, we identified six core targets, including STAT3, AKT1, PIK3CA, PIK3R1, JUN, and MAPK1, which are likely central to the mechanism of action of DLQGD in viral pneumonia." (PMID 41601832, 2026).
yolk sac tumor (1 paper, 2020). A non-seminomatous malignant germ cell tumor composed of primitive germ cells. "An analysis of 87 MOGCTs identified recurrent mutations in KIT and KRAS, along with frequent focal amplifications of PIK3CA and AKT1 in yolk sac tumors." (PMID 32455595, 2020).
cancer (4,892 papers, 2002 to 2026). A tumor composed of atypical neoplastic, often pleomorphic cells that invade other tissues. "By designing highly selective inhibitors (Compounds 1–4), the authors addressed the limitations of existing therapies and paved the way for more effective treatments for AKT1 mutation-driven cancers." (PMID 40478506, 2025). "Amplification of the AKT1 isoform is more commonly associated with cancers such as breast, lunch, ovarian, pancreatic and gastric carcinomas." (PMID 40943615, 2025). "The AKT signaling pathway is critical for tumor growth, particularly the AKT1 E17K mutation, which is found in 1.2% of all cancers." (PMID 39758787, 2025). "Mutations in AKT1, AKT2, or AKT3 are found in roughly 3–5% of cancers, with the most common functionally activating AKT mutations being E17K, L52R, and Q79K." (PMID 40080721, 2025). "Taken together, the results underscore the utility of Drosophila models in unraveling the biological relevance of AKT1 pathogenic variants in cancer." (PMID 41237900, 2025). "AKT1 (AKT Serine/Threonine Kinase 1; E17K) is a hotspot mutation that activates PI3K/AKT signaling across cancers and exists in NSCLC subsets; early clinical data with AKT inhibitors (e.g., capivasertib)." (PMID 41154602, 2025). "The EGFR-epicatechin gallate and 1-O-galloyl-beta-D-glucose-AKT1 complex have widespread interaction with cancer-associated targets, while others have fewer interactions." (PMID 40573291, 2025). "AKT1 (E17K) is a frequent somatic mutation found in several cancer types that mainly activates the PI3K/AKT signal pathway." (PMID 39329938, 2024). "Most studies have revealed that aberrant AKT1 activation causes a wide variety of disorders, including various types of cancers." (PMID 38669103, 2024). "Muhammad and colleagues examined the efficacy of D. kaki polyphenols in combating the cancer‐causing protein AKT1 (6CCY)." (PMID 39479648, 2024). "Akt1 is the core kinase subunit of the insulin growth factor pathway and has been implicated in starvation resistance in a cancer study." (PMID 38895364, 2024). "AKT1/2/3 are linked with each other in terms of their DNA sequence, but have been found to have distinct activities, particularly in cancer developement." (PMID 38836981, 2024). "In Matrigel-coated Boyden chamber assays, enhanced migration and invasion of cancer cells transformed with PIK3CA mutations were shown to depend on AKT1-mediated phosphorylation of cortactin." (PMID 38786098, 2024). "High copy of AKT1 gene has been detected in several cancers including breast and lung cancers, which has been linked to increased resistance to cisplatin." (PMID 38336976, 2024). "PIK3CAE545Q represents another activating mutation of the PI3K/AKT1 pathway, and it was found in the disseminated clone of a third triple-proficient cancer." (PMID 38175731, 2024). "It has been established that the E17K mutation in the AKT1 protein’s pleckstrin homology (PH) domain encourages protein phosphorylation and membrane localization, which, in turn, results in cancer." (PMID 38921000, 2024). "Most studies explored the incidence of the AKT1 (E17K) hotspot mutation in many cancers where glutamic acid is replaced with lysine." (PMID 39329938, 2024). "Other early signatures found in ARID1A-deficient carcinomas include the activation of the RAC (Rho family)-alpha serine/threonine-protein kinase via the increased expression of AKT1 and phosphorylation (pAKT)." (PMID 38673891, 2024). "As mutations in RAS are common to a variety of cancers many different strategies that aim to down-regulate constitutively active PI3K/Akt1 pathway have been explored." (PMID 36910637, 2023).